Y_RNA (Y RNA )
Gene: Miscellaneous RNA gene on chromosome 10 (124,766,196 to 124,766,297, forward strand). Ensembl gene ENSG00000199466.
Homologues: Orthologues: chimpanzee Y_RNA (100% identical), macaque Y_RNA (92% identical), guinea pig Y_RNA (87% identical). Paralogues in human: Y_RNA (88% identical), RNY3 (87% identical), Y_RNA (87% identical), RNY3P1 (86% identical), Y_RNA (86% identical), Y_RNA (85% identical), RNY3P14 (84% identical), Y_RNA (84% identical), RNY3P11 (83% identical), Y_RNA (83% identical), RNY3P10 (82% identical), Y_RNA (82% identical), and 96 more.